KIF14 (kinesin family member 14)
Diseases named in the same sentence as KIF14 in open-access papers (continued):
Sharing a sentence is not in itself a finding about the gene and the disease.
tumor (continued). "These miRNAs were also expressed lower in established OvCa cell lines compared to IOSE cells, suggesting that these miRNAs are interesting potential regulators of KIF14 levels in the promotion of OvCa tumor progression worthy of further characterization." (PMID 24626475, 2014). "The overexpression of KIF14 significantly reduced tumor growth compared with the controls (P = 0.0021)." (PMID 23626713, 2013). "Subsequently, the stable cell lines were subcutaneously transplanted into SCID mice to explore the effect of KIF14 on tumor growth in vivo." (PMID 23626713, 2013). "In this study, the overexpression or silencing of KIF14 in cells reduced or increased, respectively, anchorage-independent growth in vitro, and KIF14 overexpression reduced tumor growth in vivo." (PMID 23626713, 2013). "KIF14 plays an important role during mitosis, and overexpression results in error-prone mitosis and tumor progression." (PMID 19190782, 2009). "No immunoreactivity for KIF14 or E2F3 was noted in the control healthy retina, whereas KIF14 expression was localized to the nucleus and cytoplasm in tumor cells, and E2F3 expression was localized to the nucleus." (PMID 19190782, 2009). "Unlike KIF11, the expression of KIF14 did not exhibit a significant association with tumor grade in our study." (PMID 40075652, 2025). "Moreover, the regulated effects of tRF-29 on KIF14/AKT axis were also determined in the xenograft tumor assay." (PMID 40374610, 2025). "High KIF14 mRNA expression in responder group seems to be beneficial and might indicate sensitization of tumor cells to radiotherapy." (PMID 38016355, 2024). "Moreover, research on solid tumors has shown that KIF14 knockdown can suppress tumor invasion and migration." (PMID 38560563, 2024). "On the other hand, many reports point at tumor-suppressive role of KIF14 in some tumors." (PMID 38016355, 2024). "Furthermore, we identified four KIF genes as prognostic biomarkers, with experimental validation confirming the role of KIF14 in promoting tumor progression in ccRCC." (PMID 37711200, 2023). "Moreover, KIF14 exerted an oncogenic role via influencing tumor ICI and immune checkpoint-related gene expression." (PMID 36227151, 2022). "However, the expression, prognosis, mechanisms and tumor immune regulation of KIF14 in patients with LUAD remain obscure." (PMID 36227151, 2022). "The results suggest that tumor immune escape might responsible for KIF14-mediated tumorigenesis in LUAD patients." (PMID 36227151, 2022). "Inhibiting KIF14 would hinder the cell growth of neoplasms and induce apoptosis in human GBM." (PMID 35387222, 2022). "Moreover, the upregulation of KIF14 promotes tumor proliferation and inhibits apoptosis, while KIF14 downregulation suppresses tumorigenicity in vitro and in xenografts." (PMID 34495250, 2021). "In vivo, KIF14 depletion was shown to reduce tumor growth in GBM xenograft model." (PMID 34663805, 2021). "Upregulated KIF14 expression has been reported in a variety of tumours." (PMID 31139021, 2019). "KIF14 is upregulated in multiple types of tumours and act as an oncogene." (PMID 31139021, 2019). "Therefore, the specific targeting of KIF14 to inhibit tumour cell proliferation can be used to yield therapeutic benefits." (PMID 31139021, 2019). "Of course, it remains possible that sufficiently high KIF14 overexpression, beyond the levels attained in this mouse model, or genomic gain/amplification could initiate tumour formation." (PMID 30385851, 2018). "Our data suggested that KIF14 may function as a candidate oncogene through regulating genes involved in cell cycle modulation and apoptosis, thus leading to tumor progression in PCa." (PMID 28525372, 2017). "Moreover, the protein level of KIF14 is positively correlated with histological grade, clinical tumor stage and poor prognosis in patients with PCa." (PMID 28525372, 2017).
tumor (continued). "We determined that these candidate miRNAs could directly modulate KIF14 mRNA expression, indicating their importance in maintaining elevated KIF14 tumor levels." (PMID 24626475, 2014). "332H showed very low miRNA expression despite genomic gain, suggesting that multiple mechanisms (genomic gain and high KIF14 transcriptional activity) may be at play within the same tumor to ensure KIF14 overexpression." (PMID 24626475, 2014). "We have however shown that most of the primary samples demonstrate dependence on KIF14 expression for proliferative capacity, indicating that KIF14 may have a role in promoting OvCa cell survival and tumor growth." (PMID 25528264, 2014). "Furthermore, both Sp1 and YY1 expression levels correlate with KIF14 mRNA expression in primary serous OvCa tumors, demonstrating their potential role in maintaining high KIF14 levels in OvCa tumor cells." (PMID 24626475, 2014). "This could explain why in general, primary OvCa cells exhibited lower KIF14 mRNA expression in comparison to primary tumor expression after short-term growth in culture." (PMID 25528264, 2014). "Although in need of further investigation, the fact that unmethylated product is present in all normal and tumor tissues suggests a minor role for promoter methylation (of the particular region studied) in the control of KIF14 overexpression in OvCa tumor cells." (PMID 24626475, 2014). "Targeting Sp1 expression may reduce KIF14 levels in tumor cells, and could contribute to a therapeutic strategy against OvCa progression." (PMID 24626475, 2014). "If high KIF14 expression is sufficient to alter primary OvCa cell behaviour in vitro and in vivo, an oncogenic stimulus would be identified in OvCa, providing proof-of-concept for studying its tumor-promoting mechanisms." (PMID 25528264, 2014). "Further, KIF14 overexpression has a strong correlation with age at diagnosis in RB, and probably represents the amount of chromosomal/genetic instability required for tumor formation." (PMID 19190782, 2009). "Indeed, KIF14-silencing markedly enhanced the sorafenib-sensitivity of tumor cells, which could be further bolstered through the combination of KIF14-intervention and sorafenib treatment, implying that this protein may underlie sorafenib resistance in HCC." (PMID 38433242, 2024). "Thus, we concluded that the exosomes-derived miR-154-5p could inhibit ESCC tumor progression and angiogenesis through targeting KIF14." (PMID 35156510, 2022). "However, there are also studies implying the tumor-suppressive function of KIF14 in some tumors; thus, its precise role may be tumor and/or context-dependent." (PMID 34575892, 2021). "Thus, the co-overexpression of lncRNA PAXIP1-AS1 and ETS1 could accelerate tumor development and silencing KIF14 suppressed tumor growth and angiogenesis." (PMID 31823805, 2019). "Thus, our data indicate that KIF14 could act as a potential oncogene that contributes to tumor progression and poor prognosis in PCa, which may represent a novel and useful prognostic biomarker for PCa." (PMID 28525372, 2017). "Thus, our results suggest that KIF14 could act as a candidate oncogene that contributes to tumor progression and poor prognosis in PCa." (PMID 28525372, 2017). "Elevated KIF14 mRNA expression was also an indicator of poor outcomes in independent NSCLC cohorts, with higher expression observed in LUSC compared to LUAD tumours." (PMID 40002279, 2025). "Using immunohistochemical analysis of 92 tumor samples, we demonstrated that high KIF11 and low KIF14 expression correlate with poor patient outcomes, suggesting their combined evaluation offers superior prognostic value." (PMID 40075652, 2025). "Immunohistochemical analysis of 92 tumor samples showed that high KIF11 and low KIF14 expression are independent indicators of poor overall survival." (PMID 40075652, 2025).
tumor (continued). "Taken together, our studies confirmed an essential role for BUB1 in promoting the growth and metastasis of ATC tumours, which were attributed to the induction of CIN through interacting with KIF14." (PMID 38498903, 2024). "Six of them (KIF4A, ASPM, KIF20A, KIF14, TPX2, KIF18B) warrant particular attention as they show increased expression by more than 10-fold in tumor samples compared to normal tissues." (PMID 37835564, 2023). "Six of them (KIF4A, ASPM, KIF20A, KIF14, TPX2, KIF18B) are overexpressed by more than 10-fold in tumor samples and four of them (KIF11, AURKB, TPX2 and KIFC1) are essential for cell survival." (PMID 37835564, 2023). "Among these DE-MTGs, upregulated RACGAP1, RARRES3, TPX2, MMP28, GPR87, and KIF14 with HR > 1 were regarded as oncogenes, whereas downregulated TSPAN7 with HR < 1 was regarded as a tumor suppressor." (PMID 33033514, 2020). "Our study found that CENPE expression is inhibited by miR-137, while KIF14 and NCAPG expression are inhibited by miR-6500-3p, and an anti-tumor effect was achieved by combining TMZ with either miR137 or miR-6500-3p." (PMID 26933822, 2016). "This is the first report on the levels of two important candidate genes (KIF14 and E2F3) for proliferation of RB tumor simultaneously done in a larger cohort with phenotype association." (PMID 19190782, 2009). "The highly statistically significant decrease in the levels of KIF14 mRNA expression (p<0.01) and E2F3 mRNA expression (p<0.001) in chemotherapy-treated cases shows the effect of chemotherapy on proliferative tumor cells." (PMID 19190782, 2009). "Several studies have revealed the oncogenic role of NUF2, CDCA3, and KIF14 in tumor, but the mechanism has not been elucidated." (PMID 34699322, 2021). "The total expression scores for KIF11 tended to be decreased in tumor tissues relative to adjacent non-tumor tissues (p = 0.09, Mann–Whitney test), whereas for KIF14, a statistically significant increase was found (p < 0.0001, Mann–Whitney test)." (PMID 34208606, 2021). "Multivariate Cox proportional hazards models validated high KIF11 (adjusted HR = 0.32, 95% CI 0.11–0.89; p = 0.03) and KIF11+KIF14 (adjusted HR = 0.22, 95% CI 0.07–0.71; p = 0.01) as positive, and advanced tumor stage as negative, markers for OS." (PMID 34575892, 2021). "Non-tumour findings included a bilateral ballooning degeneration of lens in 12% of Kif14 transgenic mice but no wild-type mice (p = 0.02)." (PMID 30385851, 2018). "In this tumor type, disruption of the negative control operated by kinesin family member 14 (KIF14) on SKP2 seems to be responsible for SKP2 unconstrained activity." (PMID 25537506, 2015). "Immunohistochemistry confirmed KIF14 and E2F3 protein overexpression in tumor cells." (PMID 19190782, 2009). "Immunohistochemistry was done to confirm KIF14 and E2F3 protein expression in tumor cells." (PMID 19190782, 2009). "We examined whether there was a correlation between KIF14 and E2F3 mRNA expression levels in the 55 untreated tumors and various tumor phenotypes." (PMID 19190782, 2009). "However, KIF14’s role as a tumour initiator has not previously been assessed." (PMID 30385851, 2018). "However, the tumour-initiating effects of Kif14 overexpression have not been studied." (PMID 30385851, 2018). "To determine whether KIF14 overexpression in OvCa tumors could also be linked to transcriptional regulation, we measured mRNA expression of Sp1, YY1 and HSF1 in a subset of OvCa tumor tissues with (15 samples) and without (50 samples) KIF14 genomic gain." (PMID 24626475, 2014). "Despite its established role as a key regulator of cytokinesis and cell cycle progression, KIF14 expression remained relatively stable across different histological grades, suggesting that its regulation in EC may follow a distinct pattern independent of tumor differentiation." (PMID 40075652, 2025).
tumor (continued). "Positive expression of KIF14 and Mieap and negative expression of EZR were more often observed in trabecular (74.3–91.7%) and tubular structures (62.5–88.2%) as compared to other structures and single tumor cells (39.1–60.0%; p < 0.05)." (PMID 32679794, 2020). "Distant metastasis was not also related to the positive expression of KIF14 and Mieap and negative expression of EZR in other morphological arrangements of tumor cells: tubular, alveolar, solid and trabecular structures and small groups of tumor cells (data not shown)." (PMID 32679794, 2020).
adenocarcinoma (1 paper, 2013). A common cancer characterized by the presence of malignant glandular cells. "Further analysis indicated that 30.3% of the adenocarcinomas showed KIF14 down-regulation in the tumors compared with the bronchial epithelial cells in adjacent normal counterparts and that 18.0% of the adenocarcinomas showed a higher KIF14 expression than in the normal bronchial mucosa." (PMID 23626713, 2013).
KIF14 also shares sentences with these, for which no sentence is quoted: acute myeloid leukemia (3 papers); laryngeal carcinoma (2); renal cell carcinoma (2); anaplastic thyroid carcinoma (1); aneuploidy (1); autosomal recessive primary microcephaly (1); B-cell precursor acute lymphoblastic leukemia (1); Bardet-Biedl syndrome (1); blood cancers (1); bronchus tumors (1); cannabis dependence (1); ciliopathy (1); congenital heart disease (1); cyst (1); familial restrictive cardiomyopathy-6 (1); hematopoietic cancers (1); holoprosencephaly (1); lymphoid neoplasm (1); melanoma (1); memory impairment (1); mesothelioma (1); metastatic prostate carcinoma (1); multiple myeloma (1); nasopharyngeal carcinoma (1); neuroblastoma (1); rectal cancer (1); renal dysplasia (1); retinitis pigmentosa (1); rheumatoid arthritis (1); schizophrenia (1).
A further 3 diseases each share a sentence with KIF14 in 1 paper.